KCNE3 (potassium voltage-gated channel subfamily E regulatory subunit 3)
Description:
Ancillary protein that functions as a regulatory subunit of the voltage-gated potassium (Kv) channel complex composed of pore-forming and potassium-conducting alpha subunits and of regulatory beta subunits. KCNE3 beta subunit modulates the gating kinetics and enhances stability of the channel complex. Associates with KCNC4/Kv3.4 alpha subunit to form the subthreshold Kv channel in skeletal muscle and to establish the resting membrane potential (RMP) in muscle cells. Association with KCNQ1/KCLQT1 alpha subunit may form the intestinal cAMP-stimulated potassium channel involved in chloride secretion that produces a current with nearly instantaneous activation with a linear current-voltage relationship (By similarity).
Synonyms: MiRP2; HOKPP; BRGDA6; HYPP
Tractability: Small molecule: a structure with a bound ligand is known. Antibody: UniProt places it where antibodies can reach, with high confidence; its Gene Ontology location is reachable by antibodies, with high confidence; UniProt predicts a signal peptide or a membrane-spanning region; the Human Protein Atlas places it where antibodies can reach.
Gene: Protein-coding gene on chromosome 11 (74,454,841 to 74,467,743, reverse strand). Ensembl gene ENSG00000175538.
Subcellular location: Cell membrane; Cytoplasm; Perikaryon; Cell projection, dendrite; Membrane raft
Subcellular location (Human Protein Atlas): Plasma membrane
Pathways (Reactome):
Muscle contraction: Phase 2 - plateau phase; Phase 3 - rapid repolarisation
Gene Ontology:
Molecular function: potassium channel regulator activity; protein binding; delayed rectifier potassium channel activity; transmembrane transporter binding; voltage-gated potassium channel activity involved in ventricular cardiac muscle cell action potential repolarization; voltage-gated potassium channel activity
Biological process: negative regulation of delayed rectifier potassium channel activity; negative regulation of membrane repolarization during ventricular cardiac muscle cell action potential; negative regulation of potassium ion export across plasma membrane; regulation of heart rate by cardiac conduction; membrane repolarization during action potential; potassium ion export across plasma membrane; regulation of ventricular cardiac muscle cell membrane repolarization; ventricular cardiac muscle cell action potential; intracellular chloride ion homeostasis; membrane repolarization during ventricular cardiac muscle cell action potential; monoatomic ion transport; potassium ion transmembrane transport; potassium ion transport; sodium ion transport
Cellular component: cytoplasm; dendrite; membrane raft; neuronal cell body membrane; perikaryon; plasma membrane; vesicle; voltage-gated potassium channel complex; basolateral part of cell; membrane
Genetic constraint (gnomAD): Loss-of-function variants: 2 observed, 4.52 expected, observed/expected ratio (o/e) 0.44, 90% interval 0.18 to 1.36. That is too few expected variants to judge how well the gene tolerates losing a copy. Missense variants: 128 observed, 144.37 expected, observed/expected ratio (o/e) 0.89, 90% interval 0.77 to 1.03. Synonymous variants: 47 observed, 55.24 expected, observed/expected ratio (o/e) 0.85, 90% interval 0.67 to 1.09.
Gene-disease validity (ClinGen):
ClinGen rates the evidence that KCNE3 causes each of these diseases.
Brugada syndrome (autosomal dominant): Disputed. A genetically heterogeneous condition characterized by complete or incomplete right bundle branch block accompanied by ST elevation in leads V1-V3.
Homologues: Orthologues: chimpanzee KCNE3 (100% identical), macaque KCNE3 (99% identical), mouse Kcne3 (93% identical), dog KCNE3 (92% identical), pig KCNE3 (92% identical), rat Kcne3 (92% identical), guinea pig KCNE3 (91% identical), tropical clawed frog kcne3 (57% identical). Paralogues in human: KCNE5 (30% identical).
Diseases named in the same sentence as KCNE3 in open-access papers:
KCNE3 is named in the same sentence as 31 diseases in open-access papers, as found by Europe PMC text mining. Sharing a sentence is not in itself a finding about the gene and the disease. The quoted sentences say what the papers report.
Brugada syndrome (8 papers, 2011 to 2025). "Brugada syndrome mutation in KCNE3 (MiRP2) has been suggested to result in increased transient outward K+ current (Ito) and Ito channel densities in the right ventricular epicardium." (PMID 38467908, 2024).
periodic paralysis (4 papers, 2006 to 2025). "The R83H variant of KCNE3 was described in an individual with hypokalemic periodic paralysis; however, this variant was found in three of our patients none of whom had any prior episodes of paralysis and thus it appears likely that this is a rare polymorphism." (PMID 16887036, 2006). "However, a pathogenic variant of MiRP2 (KCNE3), a promiscuous accessory subunit that modulates Kv3.4 channels through a direct interaction, has been linked to a case of periodic paralysis." (PMID 40288604, 2025).
atrial fibrillation (3 papers, 2011 to 2022). A disorder characterized by an electrocardiographic finding of a supraventricular arrhythmia characterized by the replacement of consistent P waves by rapid oscillations or fibrillatory waves that vary in size, shape and timing and are accompanied by an irregular ventricular response. "The aim of this study is to investigate the potential arrhythmogenicity of three gain-of-function mutations related to atrial fibrillation—namely, KCNH2 T895M, KCNH2 T436M, and KCNE3-V17M—using modeling and simulation of the electrophysiological activity of the heart." (PMID 34135774, 2021).
Arrhythmia (2 papers, 2011 to 2022). Any cardiac rhythm other than the normal sinus rhythm. "The finding of very rare genetic variants with likely functional significance, i.e. p.M1T in KCNE3 and p.E141A in KCNE4, in controls is interesting and suggests that such variants may contribute to the arrhythmia risk in various conditions in the general population." (PMID 21967835, 2011). "Here we show that potassium voltage-gated channel subfamily E regulatory subunits 3 and 4 (KCNE3, KCNE4) are uniquely upregulated at arrhythmia sites within scarred myocardium." (PMID 35149693, 2022).
Tinnitus (2 papers, 2011 to 2020). Tinnitus is an auditory perception that can be described as the experience of sound, in the ear or in the head, in the absence of external acoustic stimulation. "The present study addresses the potassium channel subunit gene KCNE3 as a potential candidate for tinnitus susceptibility." (PMID 21899751, 2011). "We next examined whether KCNE3 variants could serve as predictors of tinnitus severity in the population under study." (PMID 21899751, 2011). "In view of the frequent association of tinnitus and hearing impairment, and of its cooccurence with Menière's disease, we hypothesized that tinnitus may be part of the phenotypic spectrum that is caused by KCNE3 variants." (PMID 21899751, 2011). "Results of the present screening are therefore preliminary with regard to a proposed functionality of KCNE3 in tinnitus." (PMID 21899751, 2011). "However, owing to a lack of power, our study can neither rule out effects of KCNE3 on the risk for developing chronic tinnitus, nor can it exclude a role in predicting the severity of tinnitus." (PMID 21899751, 2011). "It is highly likely that a mutation in KCNE3 alone may not be indicative of tinnitus, but when mutations are present in both KCNE3 and the channel with which it is interacting (e.g. KCNQ1) the biophysical properties of the channel complex are significantly altered." (PMID 21899751, 2011).
cystic fibrosis (1 paper, 2018). Autosomal recessive disorder caused by pathogenic variants in the CFTR gene (cystic fibrosis transmembrane conductance regulator), which encodes a chloride and bicarbonate channel expressed in epithelial cells, and follow the diagnosis criteria. "In epithelial cells, KCNE3 regulates the function of the KCNQ1 potassium ion (K+) channel in a physiologically critical cellular transport process in several organs and whose malfunction causes diseases such as cystic fibrosis, cholera, and pulmonary edema." (PMID 29607317, 2018).
glioblastoma (1 paper, 2016). The most malignant astrocytic tumor (WHO grade IV). "Within the potassium intermediate/small conductance calcium-activated channels, expression of 3 genes (namely KCNE3, KCNE4, KCNN4) has been found altered in the current study, namely in glioblastoma and lung adenocarcinoma." (PMID 27716384, 2016). "Within the shadowed columns, glioblastoma appears to have the highest number of modified ion-channel genes (namely: FXYD5, KCNE3, KCNE4, CLIC1, TRPM3)." (PMID 27716384, 2016).
Hearing impairment (1 paper, 2011). A decreased magnitude of the sensory perception of sound. "So far, a limited number of investigations has addressed sequence variation in KCNE3 which maps to chromosome 11q13-14, a linkage hot-spot for autosomal recessive, non-syndromal hearing impairment." (PMID 21899751, 2011).
heart failure (1 paper, 2022). Inability of the heart to pump blood at an adequate rate to meet tissue metabolic requirements. "Furthermore, we observed pro-arrhythmic genes associated with heart failure and thrombosis after MI in URI predominantly Kcne3 and Pf4." (PMID 36012110, 2022).
leiomyosarcoma (1 paper, 2021). An uncommon, aggressive malignant smooth muscle neoplasm, usually occurring in post-menopausal women. "Hypermethylation in the potassium voltage-gated channel, Isk-related family, member 3 (KCNE3), TSPY-like 5 (TSPYL5), Homeobox A11 (HOXA11), HOXA11 antisense RNA (HOXA11AS), HOX9, and LOC100130872, was observed in leiomyosarcoma." (PMID 35008848, 2021).
Menière's disease (1 paper, 2011). "A further candidate gene, encoding the potassium channel ß subunit KCNE3/MIRP2, has been adressed in Menière's disease." (PMID 21899751, 2011).
myotonia congenita (1 paper, 2021). "Intriguingly, we found a reduced KCNE3 mRNA level in muscle biopsies of two patients affected by recessive myotonia congenita (Becker’s disease), but an increase in one patient with dominant myotonia congenita (Thomsen’s disease), compared to control individuals." (PMID 34208776, 2021).
teratoma (1 paper, 2020). A non-seminomatous germ cell tumor characterized by the presence of various tissues which correspond to the different germinal layers (endoderm, mesoderm, and ectoderm). "Close examination of the tumor vasculature, however, shows that Kcne3–lacZ is specifically activated in endothelial cells localized to the microvasculature within peripheral aspects of the teratoma, which are revealed to be CD31+ ESC-derived ETCs." (PMID 31754927, 2020).
ulcerative colitis (1 paper, 2016). An inflammatory bowel disease involving the mucosal surface of the large intestine and rectum. "We therefore evaluated KCNQ1/KCNE3 channels in distal colonic crypts obtained from normal and active ulcerative colitis (UC) patients." (PMID 26718405, 2016).
Ventricular arrhythmia (1 paper, 2025). "For ventricular arrhythmia, many of the significant proteins identified by the diffusion algorithm are ion channel proteins, such as those that contribute to Ca2+ (CACNA1C, CACNA1C-IT2), Na+ (SCN3A, SCN1B, SCN4B, SCN10A), or K+ (KCNQ1, KCNE3, KCNH2) transport in the heart." (PMID 39954672, 2025).
ventricular tachycardia (1 paper, 2022). A disorder characterized by an electrocardiographic finding of three or more consecutive complexes of ventricular origin with a rate greater than a certain threshold (100 or 120 beats per minute are commonly used). "Upregulated in URI and downregulated in TRI, Kcne3 seems to be linked to ventricular tachycardia in healed MI scar and Plated factor 4 is highly expressed in URI and downregulated in TRI promoting thrombosis after MI." (PMID 36012110, 2022).
cancer (2 papers, 2016 to 2020). A tumor composed of atypical neoplastic, often pleomorphic cells that invade other tissues. "This same phosphorylation site also modifies the behaviour of KCNE3/Kv3.4 channels, which are hypoxia-regulated Kv channels involved in cancer cell migration and invasion, opening up the possibility of a general KCNE3 mediated sex difference in cancer." (PMID 33363037, 2020).
tumor (2 papers, 2020 to 2022). "Taken together, our data indicates that Kcne3 is also a specific ETC marker during tumor angiogenesis." (PMID 31754927, 2020). "In this model, all β-gal expression is attributed to Kcne3–lacZ reporter activity originating from host-derived cells invading the tumor." (PMID 31754927, 2020). "Gross inspection shows robust and specific Kcne3–lacZ activity within capillary sprouts and putative ETCs that primarily localize to the tumor perimeter." (PMID 31754927, 2020). "Second, reporter allele activity confirms that Kcne3 is specific to ETCs during developmental retinal angiogenesis, neovascular recovery following OIR, corneal injury, and in several tumor angiogenic models." (PMID 31754927, 2020). "For this purpose, we evaluated β-gal expression in Lewis Lung Cell (LLC) tumor allografts introduced subcutaneously to homozygous Kcne3–lacZ mice." (PMID 31754927, 2020). "Interestingly, a subcluster of Endo-1 was found almost exclusively in the tumor compartment, preferentially expressing known endothelial tip cell genes (KCNE3, DLL4, EDNRB, ANGPT2, and SERPINE1)." (PMID 36180422, 2022). "We also demonstrate endothelial tip-cell selectivity of Kcne3 in several injury and tumor models." (PMID 31754927, 2020). "We next asked whether Kcne3 is also upregulated during tumor angiogenesis." (PMID 31754927, 2020). "However, in contrast to Kcne3, which appears to be a universal ETC marker in multiple angiogenic contexts (retina, embryo, tumor), Esm1 loses ETC-specificity outside of the retina." (PMID 31754927, 2020).
KCNE3 also shares sentences with these, for which no sentence is quoted: channelopathies (2 papers); Alzheimer disease (1); breast carcinoma (1); cardiac arrhythmia (1); cardiomyopathies (1); congestive heart failure (1); COVID-19 (1); familial periodic paralysis (1); hypokalemic periodic paralysis (1); Jervell Lange Nielsen Syndrome (1); long QT syndrome (1); lung adenocarcinoma (1); melanoma (1).